ARID1A (AT-rich interaction domain 1A)
Diseases named in the same sentence as ARID1A in open-access papers (continued):
Sharing a sentence is not in itself a finding about the gene and the disease.
cholangiocarcinoma (29 papers, 2014 to 2025). A carcinoma that arises from the intrahepatic biliary tree (intrahepatic cholangiocarcinoma) or from the junction, or adjacent to the junction, of the right and left hepatic ducts (hilar cholangiocarcinoma). "We present a rare case of HCC arising from a large hepatic adenoma in a child, associated with an ARID1A mutation—a tumour suppressor gene implicated in several cancers, including clear cell ovarian carcinoma, gastric adenocarcinoma, and cholangiocarcinoma." (PMID 41146957, 2025). "ARID1A alterations in cholangiocarcinoma are associated with poorer survival, a higher risk for vein invasion, and a higher risk for systemic and local recurrence." (PMID 38203635, 2023). "Studies evaluating AKT inhibitors (MK-2206) in ARID1A-deficient cholangiocarcinoma cell lines revealed increased sensitivity to the drug, suggesting that targeting the PI3K/AKT pathway could improve therapeutic outcomes in these tumors." (PMID 41514650, 2025). "Similarly, a next-generation sequencing analysis of cholangiocarcinoma found chromatin modification among the most affected processes, along with ARID1A and PBRM1 being the most frequently mutated genes." (PMID 39471843, 2024). "ARID1A mutations are also more common in liver fluke-related cholangiocarcinoma." (PMID 38203635, 2023). "A precursor lesion with loss of ARID1A expression might cause a premalignant lesion of cholangiocarcinoma." (PMID 34249744, 2021). "Similarly, a high frequency of cholangiocarcinoma cases also harbor ARID1A and PI3K mutations." (PMID 41514650, 2025). "ARID1A is mutated in 7–36% of cholangiocarcinoma (CC), where it frequently co-occurs with KRAS mutations." (PMID 38275587, 2023). "ARID1A, a chromatin remodeling gene, is implicated in multiple malignancies including HCC and cholangiocarcinoma." (PMID 41146957, 2025). "A notable case report highlighted a dramatic response to mTOR-targeted therapy in a patient with intrahepatic cholangiocarcinoma harboring TSC1 and ARID1A mutations, indicating potential oncogenic dependence on mTOR in certain subtypes." (PMID 41300430, 2025). "ARID1A depletion in cholangiocarcinoma results in cellular proliferation, cell cycle escape, senescence and extensive alterations in heterochromatin." (PMID 39471843, 2024). "Meanwhile mutation in one of ARID1A and PBRM1 were found in almost half of 32 intrahepatic cholangiocarcinomas through exomic sequencing." (PMID 35672673, 2022). "Considering the role that ARID1A might play in tumor immunity, we examined immune-related signatures and gene sets in TCGA cholangiocarcinoma cohort." (PMID 35198440, 2022). "Whether in high- and low- risk, the frequent alterations in ARID1A and PBRM1 in cholangiocarcinomas highlight the key role of chromatin remodeling which in cholangiocarcinomas." (PMID 35672673, 2022). "Therefore, ARID1A may function as a tumor suppressor in cholangiocarcinoma through the transcriptional downregulation of ALDH1A1, along with a decrease in the levels of histone H3K27 acetylation." (PMID 35814382, 2022).
cholangiocarcinoma (continued). "The raw western blot images are available at figshare: Tessiri, Supharada; Jusakul, Apinya (2021): Raw data for Therapeutic Targeting of ARID1A and PI3K/AKT Pathway Alterations in Cholangiocarcinoma.zip." (PMID 35070505, 2022). "To investigate the potential mechanism of ARID1A in GBC, we investigated gene profiles using TCGA cholangiocarcinoma cohort." (PMID 35198440, 2022). "Genetic alterations in ARID1A were detected at a high frequency in cholangiocarcinoma (CCA)." (PMID 35070505, 2022). "Although genomic alterations of ARID1A have been described in various cancers, no study has examined correlations between ARID1A gene mutation and protein expression with clinicopathologic parameters and prognosis, particularly in liver fluke-related cholangiocarcinoma (Ov-CCA)." (PMID 33344089, 2020). "For example, ARID1A, a known driver gene in cholangiocarcinoma, was not significant in the relatively small TCGA_CHOL series (n = 36) but became significant when adding cryptic splice mutations." (PMID 36937541, 2023). "Alterations in chromatin remodeling genes (ARID1A, BAP1, IDH1, IDH2, PBRM1, SMARCB1) were found in 30.7% (47/153) of cancers in our series, confirming recent reports on the significant involvement of these genes in cholangiocarcinoma." (PMID 24867389, 2014).
liver cancer (29 papers, 2015 to 2026). An epithelial or non-epithelial malignant neoplasm that arises from the liver. "To investigate the malignant origin of cells in AAI‐induced liver cancer in Arid1a‐deficient mice, we identified five hepatocyte subclusters using snRNA‐seq analysis." (PMID 41133886, 2026). "Here, we demonstrate that AAI rapidly initiates liver cancer in liver‐specific Arid1a‐deficient mice." (PMID 41133886, 2026). "In a liver cancer model, Arid1a deficiency contributed to an increased number of stem/progenitor-like cells by dysregulating genes related to stemness." (PMID 39123453, 2024). "Recent advancement of cancer exome sequencing has identified ARID1A as one of the most mutated genes in human HCC, with mutations of 10%–17% in liver cancers, and remarkably ARID1A expression levels negatively correlate with survival in HCC patients." (PMID 34671561, 2021). "Previous studies have demonstrated that ARID1A deficiency can cause liver cancer metastasis, possibly due to the altered chromatin organization, however the underlying mechanisms remain poorly understood." (PMID 34689165, 2021). "This study aims to reveal the molecular mechanism of liver cancer metastasis driven by ARID1A deficiency from chromatin conformation perspective." (PMID 34689165, 2021). "This study would provide a novel insight to the ARID1A deficiency-driven liver cancer metastasis due to the chromatin organization change." (PMID 34689165, 2021). "This study provides an insight into liver cancer tumorigenesis and progression related to ARID1A mutations." (PMID 34689165, 2021). "An increasing number of studies have reported that ARID1A is associated with the OS of liver cancer patients, but the specific mechanism is still unclear." (PMID 33771191, 2021). "These phenomena deserve further elucidation to clarify the context dependency of ARID1A mutation-regulated liver cancer progression, possibly using liver cancer mouse models." (PMID 31238554, 2019). "To investigate whether ARID1A loss and β‐catenin activation synergistically drive liver cancer, we analyzed the co‐occurrence of ARID1A and CTNNB1 mutations in AA‐exposed human HCC samples." (PMID 41133886, 2026). "Given the frequent presence of the AA‐induced mutational signature SBS22a in HCC patients and the widespread use of AA‐containing herbal medicine in Asia, we investigated whether AA could initiate and promote liver cancer in the context of ARID1A loss." (PMID 41133886, 2026). "Thus, an in-depth investigation on chromatin organization is vitally important for disclosing the underlying mechanism of tumorigenesis and progression in ARID1A-mutated liver cancer." (PMID 34689165, 2021). "It has been known that ARID1A deficiency promotes liver cancer metastasis, therefore, whether these ARID1A-regulated genes can contribute to the malignant behaviors need to be confirmed." (PMID 34689165, 2021). "Then we further examined whether the dysregulated genes play crucial roles in ARID1A deficiency-driven liver cancer cell invasion." (PMID 34689165, 2021). "ARID1A nonsense/missense mutations are found in patients with liver cancer." (PMID 31238554, 2019). "However, Huang and coworkers found that mutations of ARID1A gene in primary liver cancer cause an enhanced invasiveness and metastatic ability." (PMID 26904685, 2016). "Notably, the abnormally expressed genes caused by the conformational changes due to Arid1a deficiency are significantly enriched in cancer-related processes, some of which are further verified to be involved in ARID1A deficiency-driven liver cancer cell invasion." (PMID 34689165, 2021).
liver cancer (continued). "To explore the precise role of ARID1A mutations in higher-order genome reorganization of hepatocytes, in this work, we attempt to reveal the conformational changes induced by ARID1A-deficiency, and then define the liver cancer metastasis-related genes that arose from the conformational remodeling." (PMID 34689165, 2021). "In summary, ARID1A loss and CTNNB1 activation synergistically promote liver cancer by enhancing β‐catenin signaling and tumorigenic potential, driven by AA‐induced mutational co‐occurrence." (PMID 41133886, 2026). "In a study of liver cancer, ARID1A was also found to have context‐dependent tumor suppressor and oncogenic roles." (PMID 37366273, 2023). "RT-PCR analysis was performed in Hl-7702 human benign HCC line and various liver tumor cell lines to investigate the RNA expression of ARID1A in liver cancer (Huh7, HepG2, Alex, Hep3B, Bel-7402, 97H, and, LM3)." (PMID 35028302, 2022). "ARID1A expression was related to gender (OR = 0.35, female versus male) and T classification (OR = 1.92, T3 versus T1) in liver cancer." (PMID 35028302, 2022). "Some successful and excellent prognostic models of liver cancer had published, which revealed that the expression of gene such as ARID1A, RBPs is closely related to tumor immune cell infiltration in HCC." (PMID 36061167, 2022). "As a consequence of ARID1A deficiency-induced conformational alteration, the dysregulation of some genes such as PMP22 and GSC, promoted the invasion capacity of liver cancer cells." (PMID 34689165, 2021). "The association between ARID1A/BRG1 and CTCF/RAD21 was affirmed in human liver cancer cell lines in vivo." (PMID 34689165, 2021). "Specifically, Arid1a triggered liver cancer initiation by increasing reactive oxygen species, whereas its loss in pre-existing tumours promoted cancer growth and metastasis." (PMID 33732709, 2021). "ARID1A, encoding a subunit of SWI/SNF chromatin remodeling complex, is widely recognized as a tumor suppressor gene in multiple tumor types including liver cancer." (PMID 34689165, 2021). "ARID1A alone genes were enriched for numerous gene sets involved with liver cancer and liver development." (PMID 26716708, 2015). "In fact, suppressing ARID1A increased the invasion and migration of liver cancer cells." (PMID 35028302, 2022). "This opposite effect of ARID1A is also detected in liver cancer." (PMID 34249744, 2021). "The silencing of ARID1A increased the migration and invasion abilities of the liver cancer cells." (PMID 34217266, 2021). "While ARID4A is not described in COSMIC or previous sequencing studies of liver cancer, recurrent mutations in the paralogous nucleosome remodelers ARID1A, ARID1B, and ARID2 have been previously reported in HCC21,30,35." (PMID 31796844, 2019). "ARID1A silencing increased the migration and invasion abilities of liver cancer cells." (PMID 27323812, 2016). "ARID1A may be lost later in the progression of liver cancer, according to certain research." (PMID 35028302, 2022). "Similar to AXIN1, liver specific deletion of ARID1A alone could not initiate liver cancer in mice, albeit it enhanced diethylnitrosamine (DEN)-induced hepatocarcinogenesis." (PMID 35669430, 2022).
melanoma (29 papers, 2015 to 2026). A malignant, usually aggressive tumor composed of atypical, neoplastic melanocytes. "Melanoma-private mutations in genes such as ARID1A, ARID2, PIK3CA, and CDKN2A indicated additional late events contributing to malignant progression." (PMID 41516405, 2026). "These melanoma-private mutations occurred in genes linked to chromatin regulation (ARID1A and ARID2), cell growth (e.g., PIK3CA), cell adhesion (e.g., EPHA2), splicing (SF3B1), angiogenesis (PTPRB), and classic tumor suppressors (NOTCH3, CDKN2A, and PTEN)." (PMID 41516405, 2026). "For instance, loss of ARID1A or ARID1B confers enhanced response to immune-checkpoint blockade (ICB) in melanoma and non-small cell lung cancer, whereas PBRM1 deficiency promotes primary resistance in renal cell carcinoma." (PMID 41438758, 2025). "MSKCC Cohort, mGC Cohort, and Melanoma Cohort were utilized to interrogate the predictive efficacy of ARID1A mutation to programmed cell death protein 1 (PD-1) blockade." (PMID 36369379, 2023). "We investigated the largest cohort of ARID1A mutated melanoma to date and were able to show that despite a high mutational load the described beneficial treatment response is not apparent in melanoma." (PMID 35565222, 2022). "Mutations in the ARID1A gene were otherwise found in three samples (2.6%) of patients harboring mucosal melanomas." (PMID 35565222, 2022). "ARID1A mutated melanomas harbor the greatest amount of C>T substitutions at the dipyrimidine upon comparison with Triple-WT melanoma in both absolute and relative numbers." (PMID 35565222, 2022). "In this study, we screened 3837 reports from next generation sequencing between 2013 and 2020 for ARID1A mutated melanoma and were able to identify 116 individual patients with available clinical data harboring an ARID1A mutation." (PMID 35565222, 2022). "Survival analysis of stage IV melanoma patients harboring ARID1A mutations and comparisons with previously published data did not reveal a difference in terms of overall survival." (PMID 35565222, 2022). "In melanoma, ARID1A is the third most frequently mutated SWI/SNF, occurring in 9% of melanoma tumors within the TCGA database." (PMID 35323214, 2022). "In the presented study, we retrospectively assessed a large cohort of targeted next generation sequenced melanoma from 2013–2020 and were able to identify the largest cohort of ARID1A mutated melanomas to date." (PMID 35565222, 2022). "A similar effect, accompanied by a reduction in cell invasion, was obtained in the established human melanoma cell lines LOX (ARID1A and BAP1 mutated)." (PMID 35563772, 2022). "A study utilizing sequence capture analysis of 114 melanoma patients detected loss of function mutations in ARID1A which were associated with significantly reduced expression." (PMID 35323214, 2022). "The same signature was noticeable when looking at UV-induced CC>TT substitutions, in which the greatest amount was noticed among the ARID1A mutated melanoma subtype upon comparison with Triple-WT melanoma." (PMID 35565222, 2022). "Within the group of ARID1A mutated melanomas, higher numbers of accompanying mutations were noticed compared to ARID1A WT cases." (PMID 35565222, 2022). "The aim was to better characterize the role of ARID1A mutations in melanoma, in particular, with regard to its clinical and therapeutic relevance." (PMID 35565222, 2022). "Further, ARID1A mutated melanomas predominantly appear in the male population, making up almost two-thirds of all affected patients." (PMID 35565222, 2022). "A study in which targeted next generation sequencing was conducted on 38 treatment naive melanoma patients also found ARID1B to be mutated at the same rate as ARID1A (13.2%)." (PMID 35323214, 2022). "ARID1A, frequently mutated in melanoma, is linked to resistance and immune evasion." (PMID 41708984, 2026). "They demonstrated that ARID1A mutated melanomas exhibit higher tumor mutational burden (TMB)." (PMID 36890819, 2023).